CCDC6 (coiled-coil domain containing 6)
Synonyms: D10S170; TST1; PTC; TPC; H4; PTC1
Tractability: Small molecule: an approved drug acts on it; a high-quality ligand is known. PROTAC: ubiquitination databases record sites on it; its protein half-life has been measured; a small molecule that binds it is known.
Gene: Protein-coding gene on chromosome 10 (59,788,747 to 59,907,029, reverse strand). Ensembl gene ENSG00000108091.
Subcellular location: Cytoplasm; Cytoplasm, cytoskeleton
Subcellular location (Human Protein Atlas): Cytosol
Gene Ontology:
Molecular function: identical protein binding; protein binding; structural constituent of cytoskeleton
Biological process: positive regulation of SCF-dependent proteasomal ubiquitin-dependent catabolic process; cytoskeleton organization
Cellular component: cytosol; cytoplasm; cytoskeleton
Genetic constraint (gnomAD): Loss-of-function variants: 10 observed, 30.18 expected, observed/expected ratio (o/e) 0.33, 90% interval 0.2 to 0.56. The upper end of that interval is the gene's LOEUF score, 0.56, which puts it in group 2 of 6, group 1 being the genes least tolerant of losing a copy. Missense variants: 267 observed, 416.04 expected, observed/expected ratio (o/e) 0.64, 90% interval 0.58 to 0.71. Synonymous variants: 170 observed, 173.08 expected, observed/expected ratio (o/e) 0.98, 90% interval 0.87 to 1.12.
Cancer hallmarks: genome instability and mutations (suppresses); change of cellular energetics (promotes); escaping programmed cell death (suppresses); suppression of growth (promotes)
Homologues: Orthologues: chimpanzee CCDC6 (100% identical), macaque CCDC6 (99% identical), rabbit CCDC6 (99% identical), guinea pig CCDC6 (98% identical), dog CCDC6 (97% identical), pig CCDC6 (96% identical), rat Ccdc6 (96% identical), mouse Ccdc6 (95% identical), tropical clawed frog ccdc6 (91% identical), zebrafish ccdc6b (84% identical), zebrafish ccdc6a (83% identical), Drosophila melanogaster CG6664 (50% identical), and 1 more.
Diseases named in the same sentence as CCDC6 in open-access papers:
CCDC6 is named in the same sentence as 92 diseases in open-access papers, as found by Europe PMC text mining. Sharing a sentence is not in itself a finding about the gene and the disease. The quoted sentences say what the papers report.
papillary thyroid carcinoma (25 papers, 2012 to 2026). "These rearrangements are associated with papillary thyroid carcinoma cases with different characteristics; CCDC6::RET is more associated with sporadic thyroid cancer and with older patients and classic subtypes of papillary carcinoma." (PMID 37188126, 2023). "The most frequent driver mutation in both radiation-induced and sporadic papillary thyroid carcinoma comes from the genome rearrangements between the RET gene and the PTC genes (CCDC6 and NCOA4), located close to each other on chromosome 10." (PMID 40362680, 2025). "Of note, the most common fusion in papillary thyroid carcinoma was CCDC6-RET and NCOA4-RET (41.3% and 35.8%, respectively)." (PMID 36690680, 2023). "Since discovery of the first RET fusion in thyroid cancers, at least 13 fusion partners have been identified in papillary thyroid cancers, the most common of which are coiled-coil domain containing 6 (CCDC6-RET) and nuclear receptor co-activator 4 (NCOA4)-RET." (PMID 35957881, 2022). "CCDC6-RET is the most common RET fusion in papillary thyroid cancer, which was also identified in lung cancer, acute lymphoblastic leukemia, and other cancers; detected here in breast fibrosarcoma." (PMID 36009413, 2022). "RET fusions have been described in up to one-third of papillary thyroid cancers and in 2% of lung adenocarcinoma cases; CCDC6-RET and NCOA4-RET are the most commonly identified RET fusions." (PMID 32411236, 2020). "To date, besides the first CCDC6 fusion with the tyrosine kinase RET identified in papillary thyroid cancer, additional CCDC6 fusions have been reported with PDGFRb, PTEN, FGFR2 ANK3, and UBE2D1 and with other genes in different tumor types." (PMID 31877762, 2019). "CCDC6 was first identified as a gene frequently rearranged with the RET tyrosine kinase gene in papillary thyroid cancers." (PMID 28653990, 2017). "CCDC6 was identified upon rearrangement with RET in papillary thyroid carcinomas (PTC) generating the RET/PTC1 oncogene detectable in about 20% of PTCs." (PMID 25970781, 2015). "To further understand the role of CCDC6 in PP4c activity modulation we utilized a human CCDC6-null cell line, the thyroid papillary carcinoma TPC-1 cell line, that carries the RET/PTC1 oncogene and has lost by deletion the normal unrearranged CCDC6 allele." (PMID 22655027, 2012). "The RET/papillary thyroid carcinoma 1 (PTC1) oncogene, frequently found in human papillary thyroid carcinomas, involves the fusion of RET’s kinase domain with the initial 101 amino acids of CCDC6, leading to allelic expression loss and influencing thyroid cancer development." (PMID 39457720, 2024). "CCDC6 was first identified in papillary thyroid carcinoma as a result of the rearrangement of an unknown amino-terminal sequence with the tyrosine kinase domain of the RET proto-oncogene." (PMID 39684377, 2024). "TheRET fusion genes discovered in these studies include CCDC6-RET (already known as RET/PTC1 in papillary thyroid carcinoma) as well as a novel fusion with KIF5B (kinesin family member 5B), encoding a coiled coil domain, generated by pericentric inversion in chromosome 10." (PMID 27429741, 2016). "Three cases were characterized by NCOA4-RET, CCDC6-RET, and SND1-BRAF fusions, which are more commonly seen in papillary thyroid carcinoma." (PMID 33441414, 2021). "Perhaps most notably, one of the fusions involves CCDC6 and c-RET kinase, which is seen frequently in papillary thyroid carcinoma." (PMID 23405175, 2013). "The data presented here define that CCDC6, a partner of RET in papillary thyroid carcinoma and in lung adenocarcinoma, fine modulates the CREB1-dependent transcriptional activity through sumoylation both in vitro and in vivo." (PMID 23145146, 2012). "Thus, this study aimed to determine the prevalence of CCDC6::RET and NCOA4::RET fusions in Thai papillary thyroid carcinoma patients." (PMID 37188126, 2023).
papillary thyroid carcinoma (continued). "Papillary thyroid cancer is characterized by chromosal rearrangements, through which the promoter and the primary sequences of a genes (R1α- NcoA4- RFG5- hTIF1- CCDC6- RFG7/hTIFR) are transferred to the terminal sequences of the RET gene, developing a fusion gene." (PMID 23815863, 2013). "Notably, CCDC6-RET fusion was detected in 17 cases, which may be related to 16 patients with papillary thyroid carcinoma or microcarcinoma (PTC/PTMC) and one benign case with concurrent molecular alteration." (PMID 37744220, 2023).
lung carcinoma (23 papers, 2014 to 2026). "Vepafestinib also inhibited the growth of multiple lung cancer patient-derived cell lines harboring RET fusions with different N-terminal partners (CCDC6, KIF5B, TRIM33) and a RETC634W-mutation-positive MTC cell line." (PMID 37743366, 2023). "In the contest of BReast CAncer gene (BRCA)-mutated cancers with compromised HR repair, low CCDC6 protein levels can increase lung cancers cells’ sensitivity to olaparib alone or synergize with chemotherapy." (PMID 31817541, 2019). "In this work, we analyze the effects exerted by the CCDC6 mutated isoforms on lung cancer cells." (PMID 31877762, 2019). "Thus, given the defects in HR repair caused by CCDC6 loss, we hypothesized that CCDC6 defective lung cancer cells should have been sensitive to treatment with olaparib." (PMID 28653990, 2017). "These associations include APC/CDC20 for EML4-ALK fusions in lung cancers, SPOP for NUP98-NSD1 and BCR-ABL fusions in LAML, and FBW7 (or FBXW7, F-box and WD repeat domain containing 7) for CCDC6-RET fusions in thyroid carcinomas (THCAs)." (PMID 34795215, 2021). "Few genes are recurrent partners in tyrosine kinase fusions in lung cancer, including CCDC6, a recurrent partner in ROS1 and RET fusions, that can be selected as possible target for new strategies of combined therapy including TKi." (PMID 29455670, 2018). "So, here, on the basis of our recent findings on the role of the tumor suppressor CCDC6 protein in lung tumorigenesis, we will also discuss novel therapeutic approaches we envision for lung cancer." (PMID 28653990, 2017). "Accordingly, lung cancer cells expressing low levels of CCDC6 have severe defects in the homologous recombination (HR) DNA repair pathway induced by DSBs." (PMID 28653990, 2017). "On the basis of the results obtained in NSCLC and SCLC-derived cell lines and in tumor samples, we envision CCDC6 as a biomarker for a more personalized lung cancer therapy." (PMID 28653990, 2017). "We focused on three missense mutations (L217P, A226S, P442S) in patients with HGSOC, which, despite their location, could affect CCDC6 function and localization, similar to what is seen in non–small cell lung cancer." (PMID 41417832, 2026). "RET is fused with genes such as KIF5B or CCDC6 in approximately 1% of lung cancers." (PMID 30943926, 2019). "In this work, we demonstrated that the transient expression of the CCDC6 lung mutant or truncated isoforms in lung cancer cells determined a trend of cis-platinum resistance and Olaparib sensitivity as previously observed in the same cells stably silenced for CCDC6." (PMID 31877762, 2019). "Interestingly, the activation of CCDC6-RET has been identified in post progression samples of lung cancer patients, which developed resistance to EGFR TKIs." (PMID 29455670, 2018). "Moreover, we will discuss new therapeutic options we suggest on the basis of our recent findings on the role of the tumor suppressor CCDC6 protein in lung cancer." (PMID 28653990, 2017). "Indeed, we have demonstrated that low levels of CCDC6 protein increase lung cancer cells’ sensitivity to the sole olaparib treatment; moreover, olaparib synergizes with cisplatinum in killing cells." (PMID 28653990, 2017). "Thus, we reasoned that P5091, an Usp7 inhibitor, lowering CCDC6 levels, should sensitize even lung cancer cells that express normal level of the protein to olaparib." (PMID 28653990, 2017). "The CCDC6-RET fusion kinase in patient 1 occurred at a novel breakpoint at CCDC6 intron 2 and RET intron 10 from a chromosome 10 inversion event, which differs from the CCDC6-RET fusion kinase breakpoints in thyroid cancer and lung cancer that fused CCDC6 exon 1 to RET exon 12-20." (PMID 26078337, 2015). "Thus, the CCDC6 characterization in lung cancer patients may define indications to select group of patients who could benefit of PARP-inhibitors treatment in combination with standard therapies." (PMID 31877762, 2019).
lung carcinoma (continued). "The coiled coil domain was found in FGFR2::CCDC6 (breast cancer, iCCA), FGFR2::CIT (lung carcinoma), and FGFR2::KIAA1967 (lung squamous cell carcinoma) fusions, all of which exhibited constitutive dimerization." (PMID 37370984, 2023). "RET fusions have been identified in 5–10% of papillary thyroid cancers and 1–2% of lung cancers and involve distinct fusion partners, including KIF5B in lung adenocarcinoma and CCDC6 in thyroid and lung cancer." (PMID 35510953, 2022). "In contrast, some of the low frequency fusions, CCDC6-RET in thyroid and NSCLC lung cancer, FGFR2-BICC1 in cholangiocarcinoma, PTPRZ1-MET and KIF5B-RET in non-small cell lung (NSCLC) cancer (≤5 fusions detected) did show linkage to tumour type." (PMID 35984852, 2022). "In a previous report, we detected 15 RET fusion transcripts in cells taken from a lung cancer patient and confirmed five RET fusion partners (KIF5B, CCDC6, TRIM33, NCOA4, and CUX1)." (PMID 27150058, 2016). "In the LC2AD lung cancer cell line, the TSC of the CCDC6 gene was physically connected to the PAS of the RET gene; the two genes were separated by more than 3 Mb and located on opposite strands of chromosome 10." (PMID 25034687, 2014). "In contrast to 13 fusion partner genes of RET in thyroid carcinoma, only KIF5B-RET, CCDC6-RET, TRIM33-RET and NCOA4-RET have been reported in lung cancer, and KIF5B-RET is the most commonly identified gene fusion in NSCLCs to date." (PMID 25047660, 2014). "In contrast, less prevalent actionable fusions exhibited tumour type specificity including CCDC6-RET fusions in thyroid and lung cancer, FGFR2-BICC1 in cholangiocarcinoma, PTPRZ1-MET in glioblastoma, EIF3E-RSPO2 and PTPRK-RSPO3 in colorectal cancer and KIF5B-RET in NSCLC as previously reported." (PMID 35984852, 2022). "Given the prevalence of CCDC6 fusion to ROS1 and RET, this analysis will identify and tailor a treatment, with the aim to enhance the TKI efficacy and to prevent resistance in almost 1000 lung cancer patients." (PMID 29455670, 2018). "We also speculate on the role of CCDC6 as common partner of at least two TK, ROS1 and RET, for its targeting in combined therapies including TKIs in lung cancer treatment." (PMID 29455670, 2018). "We demonstrated that the transcription levels of ALK- or RET-fusion partner genes, such as EML4, CCDC6 and KIF5B, were constitutively activated in lung cancer cells, and the expression at the C-terminal region of ALK, RET, or ROS1 was also markedly elevated in each fusion-positive lung cancer cell." (PMID 30943926, 2019). "For example, in a study using a split FISH assay to evaluate 1528 lung cancers, 22 tumors were detected with split RET signals, of which 12 were confirmed as fusions with KIF5B and one with CCDC6 and the remaining nine tumors showed little or no expression of the RET kinase domain." (PMID 25881079, 2015).
thyroid cancer (19 papers, 2014 to 2025). "Thyroid carcinoma (THCA) demonstrated the highest rate of coiled-coil domain containing 6 (CCDC6)-RET fusions, which constitutively activate RET kinase." (PMID 35978072, 2022). "Expression of human CCDC6-RET in zebrafish was associated with robust thyroid proliferation, activation of ERK signaling, development of thyroid carcinoma within weeks, and adaptive resistance after exposure to a selective RET inhibitor." (PMID 35510953, 2022). "This is amplified by the fact that the fusion proteins originating from the majority of the detected driver mutations, namely those of RET, NTRK3, CCDC6 (when co-occurs with RET), and MET, can be effectively targeted with small tyrosine kinase inhibitors in thyroid cancer." (PMID 39409115, 2024). "The frequency of CCDC6::RET in sporadic thyroid cancer is higher than that of NCOA4::RET." (PMID 37188126, 2023). "Taken together, the results indicate that the sumoylation of the tumor repressor CCDC6 may be a factor involved in thyroid cancer, providing an additional mechanism of sustained neoplastic growth." (PMID 35406382, 2022). "Our data suggest that SHP2 may play a unique role in modulating ERK pathway activation in CCDC6-RET–rearranged thyroid cancer cells, and that pSHP2 and pSTAT3 may be biomarkers of adaptive resistance to RET inhibition." (PMID 35510953, 2022). "Third, because we can only conduct WES with FFPE samples, it is impossible for us to detect the fusion genes commonly reported in thyroid cancer (e.g., CCDC6-RET and NTRK fusions), which could be the driver genomic event in the primary tumor of our patient and shared by all the metastatic samples." (PMID 34249677, 2021). "The most common RET fusions in PTC are CCDC6-RET (RET/PTC1) and NCOA4-RET (RET/PTC3), found in 90% of fusion-positive cases, whereas other follicular-derived thyroid cancers rarely harbour RET fusions." (PMID 40332222, 2025). "Chromosomal rearrangements involving genes known to be translocated in thyroid cancer were found in two samples, including one case with RET rearrangement involving the common RET partner CCDC6 and one case with the PAX8::PPARG fusion." (PMID 41123735, 2025). "But the fusion of CCDC6 and RET in thyroid cancer cells abrogates the ability to combine with CREB1 so as to activate CREB1." (PMID 36186907, 2022). "Analysis of lung and thyroid cancer tissues showed a positive rate by RET fusion partners such as KIF5B and CCDC6, and their sensitivities were 100%." (PMID 34497761, 2021). "The RET/PTC1 (CCDC6-RET) is the most common rearrangement, accounting for 60% of thyroid cancer with RET rearrangements, followed by RET/PTC3 (NCOA4-RET, 30%), and RET/PTC2 (PRKAR1A-RET, 5%)." (PMID 31835496, 2019). "Previously reported fusion genes in thyroid cancer, ETV6–NTRK3 (4.80% in PTC), CCDC6–RET (2.40% in PTC), NCOA4–RET (0.80% in PTC), SQSTM1–NTRK1 (0.80% in PTC), STRN–ALK (0.80% in PTC), and PAX8–PPARG (0.80% and 1.82% in PTC and FTN, respectively), were also identified." (PMID 27494611, 2016).
non-small cell lung carcinoma (10 papers, 2015 to 2025). A group of at least three distinct histological types of lung cancer, including non-small cell squamous cell carcinoma, adenocarcinoma, and large cell carcinoma. "Among the USP7 substrates involved in the cell cycle processes, Coiled-coil domain-containing protein 6 (CCDC6) proved to carry out an important role in non-small cell lung cancer (NSCLC)." (PMID 41157055, 2025). "In roughly 1% of non small cell lung cancers (NSCLC), particularly in adenocarcinoma, chromosomal inversions cause the fusion of the RET-encoded TK domain to different exons of KIF5B (kinesin family member 5B) gene or, less commonly, to CCDC6, NCOA4 or TRIMM33." (PMID 26046350, 2015). "CCDC6-RET and NCOA4-RET have been previously characterized as oncogenic and occur recurrently in papillary thyroid and non-small cell lung cancers." (PMID 34650924, 2021). "Using a genomics guided outlier approach, we identified 4 RET fusion PDX models with 3 different fusion partners (KIF5B, CCDC6, and NCOA4) in both non-small cell lung cancer and colorectal cancer." (PMID 30038711, 2018). "Somatic RET rearrangements (as fusion genes with CCDC6, NCOA4, KIF5B, PRKAR1A, TRIM33 and other rarer partners) have now been found in 1–2% of non-small-cell lung cancers (NSCLC) and at lower prevalence in many other cancers including pancreatic, colon, breast and salivary gland." (PMID 39655713, 2025).
lung adenocarcinoma (7 papers, 2012 to 2026). A carcinoma that arises from the lung and is characterized by the presence of malignant glandular epithelial cells. "We report a case of EGFR exon 19-mutant lung adenocarcinoma that developed an acquired CCDC6-RET fusion following treatment with first-line osimertinib, identified through repeat molecular profiling at disease progression." (PMID 41694974, 2026). "Previously unidentifed CCDC6-RET fusions have been recently described in lung adenocarcinoma." (PMID 23145146, 2012). "Other top recurrent fusions include EML4–ALK in lung adenocarcinoma (LUAD; 1.0%), CCDC6–RET in THCA (4.2%), and FGFR2–BICC1 in cholangiocarcinoma (CHOL; 5.6%)." (PMID 29617662, 2018).
colorectal cancer (6 papers, 2018 to 2024). A primary or metastatic malignant neoplasm that affects the colon or rectum. "However, a study conducted in colorectal cancer demonstrated that the CCDC6::RET fusion is mutually exclusive with other important driver mutations, such as KRAS, BRAF and PIK3CA." (PMID 39684377, 2024). "Here, we describe a novel gene rearrangement (CCDC6::CASP7) detected in a patient with advanced colorectal cancer that could be a therapeutic target." (PMID 39684377, 2024). "In addition, CCDC6-RET was only detected in non-colorectal cancers." (PMID 36369474, 2022). "On the other hand, Le Rolle and co-workers have recently reported on the identification and characterization of RET fusions that juxtapose the C-terminal RET kinase domain to the N-terminal domain of CCD6 or NCOA4 (CCDC6-RET and NCOA4-RET fusions) in advanced colorectal cancer." (PMID 29665843, 2018).